FLG (filaggrin)
Diseases named in the same sentence as FLG in open-access papers (continued):
Sharing a sentence is not in itself a finding about the gene and the disease.
eczema (89 papers, 2009 to 2025). "Loss of filaggrin leads to reduced skin barrier integrity, increased water loss, and a predisposition to develop eczema." (PMID 39721985, 2025). "The hallmark of eczema is epidermal barrier dysfunction, characterized by reduced filaggrin (FLG) expression, impaired stratum corneum cohesion, and dysregulated ECM metabolism." (PMID 41246327, 2025). "Certain alleles (e.g., filaggrin mutations in eczema, TGF-β pathway variants in keloids) are more prevalent in populations with skin of color, increasing disease risk and severity." (PMID 40677472, 2025). "This includes skin barrier defects such as filaggrin mutations leading to increased rates of eczema and subsequent food and aeroallergen sensitization." (PMID 39721985, 2025). "Among these, four had Pathogenic variants in the FLG gene, which is associated with a wide spectrum of skin disorders ranging from eczema to ichthyosis." (PMID 38256266, 2024). "Several molecular markers expressed in the skin have been implicated in the pathogenesis of eczema, including filaggrin, aquaporin-3, and interleukin-31." (PMID 38138183, 2023). "Filaggrin is a protein that binds keratin fibers in epithelial cells and filaggrin mutations have been associated with predisposition to eczema, a disorder of the skin where S. aureus is a standard commensal or pathogen." (PMID 37767091, 2023). "FLG gene loss-of-function variants are the best known genetic factors contributing to epidermal barrier impairment and eczema severity." (PMID 37533579, 2023). "We aimed to explore if reduced skin barrier function by high transepidermal water loss (TEWL), or manifestations of eczema or Filaggrin (FLG) mutations, were associated with lower lung function in three-month-old infants." (PMID 36670639, 2022). "In the present study, HRNR and FLG2 risk variants predicted the future development of eczema-associated asthma with a positive predictive value of approximately 50%, which improved considerably when these variants were combined with FLG mutations." (PMID 36013110, 2022). "Our primary aim was to explore if high TEWL, and secondarily manifestations of eczema or FLG mutations were associated with lower lung function in healthy three-month-old infants." (PMID 36670639, 2022). "Unique filaggrin loss‐of‐function mutations have also been identified in black children with eczema." (PMID 33179341, 2021). "An impaired skin barrier in humans resulting from eczema or filaggrin mutations is associated with increased prevalence of food allergy." (PMID 35387036, 2021). "Mouse models have been developed that mimic eczema, including flaky tail (filaggrin deficient) mice and in BALB/c mice with tape stripping, which removes the stratum corneum layer of the skin." (PMID 35387036, 2021). "Eczema is associated with loss-of-function mutations in FLG, the gene encoding filaggrin—a multi-functional protein that contributes to skin barrier integrity." (PMID 32087126, 2020). "In fact, this possibility has been well documented for the filaggrin protein, encoded by the FLG gene, and functional defects resulting from loss-of-function mutations of FLG have been found to be a major risk factor for eczema." (PMID 32731431, 2020). "Filaggrin (FLG) variants are specifically associated with eczema, whereas other genome-wide significant loci such as IL6R show almost perfect symmetry in association with each of the 3 diseases." (PMID 32642022, 2020). "Evidence showed that mutations in the filaggrin gene have been strongly associated with the development of eczema." (PMID 32806653, 2020). "For example, loss-of-function mutations in filaggrin (FLG) are a major risk factor for human eczema." (PMID 31631836, 2019). "In mice, in utero exposure to TCDD increased epidermal barrier formation via activation of the AhR and increased expression of the filaggrin gene; a deficiency and mutation in filaggrin has been associated with eczema." (PMID 29482571, 2018).
eczema (continued). "A review showed that approximately 70% of patients with severe eczema developed asthma or allergic rhinitis later in life, and asthmatic patients who had filaggrin mutations had a difficult disease course with more asthma exacerbations." (PMID 28536690, 2017). "Research has shown that the development of eczema can be associated with mutations of the filaggrin gene that is responsible for a major structural protein in the epidermis." (PMID 28536690, 2017). "On the contrary, children with the filaggrin mutation had a significantly higher risk of developing eczema if they lived together with older brothers or sisters." (PMID 30402607, 2017). "Studies have shown that a mutation in the filaggrin gene predisposes subjects to the development of eczema and mutations in the filaggrin gene are common among subjects with eczema." (PMID 27493721, 2016). "Filaggrin contributes to the hydration and pH homeostasis of the stratum corneum, and mutations of the filaggrin gene are associated with ichtyosis vulgaris and eczema." (PMID 27023475, 2016). "Compared with eczema alone, the excess risk of these loci on the atopic march was not significant although a trend for FLG-null mutations and the C11orf30/LRRC32 locus was observed." (PMID 26542096, 2015). "Previous studies have found that whole body impedance is associated with steroid treatments and several types of cutaneous reactions, including an indirect association to Filaggrin-related eczema (via stratum corneum hydration)." (PMID 25077568, 2014). "Several studies have shown that FLG mutations predispose to asthma but only in the context of prior eczema or AD and their families, which indicating that FLG mutations did not have an independent effect on asthma." (PMID 24858702, 2014). "Eczema has been identified as a significant risk factor for peanut allergy, and the filaggrin mutations often seen with eczema represent a significant risk factor for IgE-mediated peanut allergy." (PMID 24112405, 2013). "It was found that (exclusive) breastfeeding increased the risk of eczema after adjustment for demographics, filaggrin variants, parents’ eczema, and pets at home (n=306; RR 2.09 [95% CI: 1.15, 3.80]; p=0.016)." (PMID 23589711, 2013). "The discovery of loss-of-function variants in the filaggrin gene and their successful association with eczema in multiple studies has shed light on the importance of skin barrier genetics." (PMID 23815671, 2013). "A number of genetic variants that result in null expression of filaggrin, are associated with impaired skin-barrier function, increased risk of eczema, and eczema further complicated by asthma." (PMID 22471265, 2012). "Null (Loss-of-function) variants in the FLG gene have been linked to disrupted skin barrier and are strong predisposing factors in the development of eczema." (PMID 22403702, 2012). "Genetic factors, such as the common loss of function mutations within the filaggrin gene, are a risk factor for incident eczema and account for skin barrier dysfunction." (PMID 22839963, 2012). "A defective skin barrier due to mutations in the gene encoding profilaggrin/filaggrin (FLG) is associated with increased trans-epidermal water-loss, dry skin, itching and eczema." (PMID 23095804, 2012). "Mutations in the gene encoding filaggrin (FLG) have been identified as a strong predisposing factors for eczema and especially severe phenotypes of the disease, but other candidate genes are also under investigation." (PMID 21599876, 2011). "Although effect size is small in a population setting, filaggrin haploinsufficiency is a highly penetrant trait, and associated with increased eczema severity." (PMID 21599876, 2011). "Our 511 pediatric eczema cases include the discovery cohort for FLG loss-of-function mutations and are very well characterized for the prevalent and rare FLG null variants." (PMID 20109745, 2010).
eczema (continued). "In conclusion, filaggrin haploinsufficiency is a highly penetrant trait, associated with ichthyosis, keratosis pilaris, palmar hyperlinearity and flexural eczema, with a statistically significant trend towards more severe eczema." (PMID 19681860, 2009). "Loss of filaggrin function seems to play a role both in the pathogenesis of eczema and the subsequent progression of atopy." (PMID 18818269, 2009). "The pathogenesis of eczema arises from complex interactions among genetic susceptibility (e.g., filaggrin (FLG) mutations), impaired skin barrier function (e.g., elevated pH and microbial dysbiosis), dysregulated immune responses (including Th2/Th17 imbalance), and environmental factors." (PMID 41246327, 2025). "One study has reported that filaggrin mutations are linked to infantile eczema and AD." (PMID 40417699, 2025). "Individuals carrying filaggrin gene mutations are not only at a higher risk of developing skin dryness on the trunk and extensor surfaces of the limbs in infants aged 3–6 months, but they also face an increased risk of developing eczema and AD." (PMID 40417699, 2025). "Filaggrin—are there more eczema risk genes in the epidermal differentiation complex?" (PMID 38835414, 2023). "FLG gene mutations, however, explain up to only 50% of AD/eczema cases." (PMID 37020647, 2023). "Filaggrin SNPs are associated with an increased risk of asthma and food allergy as well as eczema." (PMID 35458152, 2022). "In the current analysis, we aimed to ascertain early‐life predictors of peanut allergy and address a specific hypothesis that early‐life eczema and FLG loss‐of‐function mutations are independent risk factors." (PMID 35108754, 2022). "If household members intake peanuts frequently, hands and saliva may be potential sources for direct or indirect contact with an infant’s disrupted skin barrier (due to eczema, filaggrin mutation, or increased transepidermal water loss)." (PMID 32344804, 2020). "Therefore, future studies with larger sample sizes are needed to examine the potential mediating role of filaggrin mutations on the associations of eczema phenotypes with asthma and allergic conditions, and the role of different ethnicities." (PMID 32099644, 2020). "In GINIplus and LISAplus, we investigated whether older siblings have a protective effect on eczema development and whether mutations in the filaggrin gene (FLG), which is decisive for an intact skin barrier, modify the “sibling effect”." (PMID 30402607, 2017). "As peanut sensitization is strongly related to loss-of-function variations in the filaggrin gene found in eczema and to asthma, the relationship between peanut sensitization and peanut allergy may be confounded by eczema and asthma." (PMID 24112405, 2013). "Furthermore, we confirmed the well-established role of FLG mutations in eczema showing that German children in the PARSIFAL material with a 2282del4 deletion in the FLG gene had an increased risk to develop allergic eczema (OR=5.9, CI 2.7-12.9)." (PMID 24260339, 2013). "There is a debate as to whether allergic sensitization and filaggrin gene (FLG) variants lead to eczema or FLG variants and eczema increase the risk of allergic sensitization." (PMID 22403702, 2012). "Filaggrin contributes to the skin barrier and mutations of FLG have been associated with eczema." (PMID 21603163, 2011). "The penetrance with respect to skin signs known to be associated with FLG haploinsufficiency (summing ichthyosis, keratosis pilaris, palmar hyperlinearity and flexural eczema) is 100% in homozygotes, 87·8% in heterozygotes and 46·5% in wild-type homozygotes (P< 0·0001, Fisher exact test)." (PMID 19681860, 2009). "Furthermore, in this cohort the association of FLG null mutations with the combined ichthyosis and/or keratosis pilaris and/or hyperlinear palms and/or eczema group persists when the 10 cases of ichthyosis vulgaris are excluded from analysis (P< 0·0001)." (PMID 19681860, 2009).
eczema (continued). "Another possibility is that underlying immune dysregulation or skin characteristics, such as dry skin due to reduced levels of natural moisturizing factor and loss of function mutation in the filaggrin gene, prior to eczema development might benefit S. aureus growth." (PMID 33759242, 2021). "Importantly, it has also been shown that almost 50% of all severe cases of eczema may have at least one mutated filaggrin gene." (PMID 30473631, 2018). "The lesions in eczema are flexural in distribution and demonstrate lack on filaggrin on histopathological examination." (PMID 39165496, 2024). "Some of the underlying genes, such as FLG, IL6R, CARD11, and IL2RA, were also reported in GWAS on eczema, others were located in or near eczema susceptibility loci." (PMID 38835414, 2023). "Eczema treatment is directed towards decreasing inflammation and restoring the skin barrier, which allows for restoration of filaggrin function." (PMID 36118171, 2022). "Several studies have also suggested that the filaggrin gene (FLG) plays a role in the development of eczema." (PMID 36686099, 2022). "Selecting variants based on the deleteriousness score (CADD) in combination with the variance-component test (SKAT) performed best for the different scenarios and identified FLG, DUSP1, and NOTCH4 to be significantly associated with eczema in RV set." (PMID 34785669, 2021). "The role of the filagrin gene FLG has been suggested in the development of eczema; FLG is the main gene aggregates intermediate keratin filaments, and patients with acute eczema have reduced FLG activity." (PMID 34399722, 2021). "All significantly associated genes within the EDC and within the MHC disappeared suggesting that the best-associated genes FLG and NOTCH4 represented the main eczema-susceptibility genes in these regions." (PMID 34785669, 2021). "As identified in RV set, MAGMA confirmed FLG, DUSP1, and NOTCH4 to be significantly associated with eczema in the complete data set." (PMID 34785669, 2021). "Filaggrin (FLG) loss-of-function mutations contribute to an impaired skin barrier and are associated with eczema and a range of allergic conditions, as well as allergic sensitization." (PMID 31629803, 2020). "This protease plays a key role in profilaggrin-filaggrin processing and reduced expression in mice leads to an eczema phenotype." (PMID 25614765, 2014). "Mutations in the FLG gene are known to be associated with the development of AD/eczema because the lack of the structural protein filaggrin leads to impairment of the barrier function of the skin." (PMID 37020647, 2023). "Compared to normal skin, filaggrin expression is significantly reduced in acute eczema." (PMID 38138183, 2023). "Similar to eczema, in EoE as therapies decrease inflammation, filaggrin function may improve and the barrier defect restored." (PMID 36118171, 2022). "FLG mutations are linked to higher TEWL, eczema, AD, allergic sensitization and asthma severity." (PMID 36670639, 2022). "Th2 inflammation down-regulates filaggrin, which leads to barrier defects in eczema." (PMID 36118171, 2022). "Neither a high TEWL, nor eczema or FLG mutations were associated with the continuous tPTEF/tE in the multivariate analyses." (PMID 36670639, 2022). "A possible mechanistic link between eczema and EoE responsiveness lies in tissue barrier function via filaggrin, an epithelial protein that aids in the structure and function of the stratum corneum and plays a key role in pathogenesis of eczema and food allergy related inflammation." (PMID 36118171, 2022). "For example, population genetics studies have identified three filaggrin mutations in East Asian eczema populations that are not present in the white European eczema population." (PMID 33179341, 2021). "Unfortunately, we were not able to study filaggrin mutations as mediators for the association of eczema phenotypes with asthma and allergic conditions due to lack of power." (PMID 32099644, 2020).
eczema (continued). "Mutations of filaggrin (FLG), an important structural protein in the stratum corneum of the epidermis, has been identify as an important predisposing factor in the development of eczema." (PMID 29516688, 2018). "A population-based, longitudinal birth cohort study from the U.K. found that impairment in the skin barrier due to mutations in the FLG gene was associated with an increased risk of eczema, both atopic and non-atopic." (PMID 23095804, 2012). "However, 40% of the carriers of filaggrin null alleles never experience eczema, and the contribution of the other barrier protein dysfunction in AD pathogenesis is far from being demonstrated." (PMID 36359220, 2022). "Furthermore, filaggrin breakdown increases skin dryness, and then eczema symptoms develop." (PMID 36686099, 2022). "FLG loss‐of‐function mutations were associated with peanut allergy in children without eczema." (PMID 35108754, 2022). "Besides a variety in clinical presentation (e.g. presence of the eczema in the flexures vs. nonflexural eczema), some have described distinct subtypes based on nonclinical features [e.g. presence of filaggrin (FLG) mutations or serum immunoglobulin E (IgE)]." (PMID 35170821, 2022). "The questionnaires we used focused on reproductive disorders and not skin or atopic disorders; hence, we did not ask specifically for information about eczema or the use of medication for skin conditions that could be related to filaggrin deficiency." (PMID 24380925, 2014). "It is noteworthy that approximately 46·5% of FLG wild-type individuals also demonstrated ichthyosis, keratosis pilaris, palmar hyperlinearity and/or eczema, which may be a result of filaggrin downregulation by other genetic and/or environmental factors or by filaggrin-independent mechanisms." (PMID 19681860, 2009). "Filaggrin research in the McLean laboratory is supported by grants from the British Skin Foundation, National Eczema Society, Medical Research Council (reference number G0700314) and anonymous donations from families affected by eczema in the Tayside Region of Scotland." (PMID 19681860, 2009). "The exceptions were four variants located on chromosomes 1q21.3 (in/near TCHHL1, HRNR, FLG and SPRR2A) which had significantly stronger effects on age-of-onset of eczema, and one on 17q12 (in GSDMB) which had a stronger effect on the age-of-onset of asthma." (PMID 32603359, 2020). "Four of these had a stronger effect on the age-of-onset of eczema: those in/near HRNR (rs1213821), FLG (rs61816761), TCHHL1 (rs115045402), SPRR2A (rs184587444), all within a 1 Mb locus on chromosome 1q21." (PMID 32603359, 2020). "With their slow but consistent development of pruritus and eczema, PAR2OE mice mimic the clinical course of AD in children closer than other mouse models of AD (e.g., flaky tail mouse, SPINK5−/−, or filaggrin−/−)." (PMID 32903402, 2020). "GWAS have highlighted distinct SNPs only expressed on genes in epithelial but not immune cells which increase the risks of eczema (filaggrin SNPs) or asthma (A Dysintegrin And Metalloprotease33—ADAM-33) with or without allergy." (PMID 35458152, 2022). "Thus, we recruited adult AD patients and age‐matched healthy controls, and assessed their filaggrin (FLG) genotype, serum IgE level, and eczema area and severity index (EASI)." (PMID 30515983, 2019). "The four loci originally discovered through GWAS on eczema (FLG, IL4/KIF3A, OVOL1 and C11orf30/LRRC32) did not reveal an effect on asthma alone." (PMID 26542096, 2015).